ELMO3 (engulfment and cell motility 3)
Diseases named in the same sentence as ELMO3 in open-access papers (continued):
Sharing a sentence is not in itself a finding about the gene and the disease.
tumor (11 papers, 2014 to 2023). "In this context, ELMO3 transcript and protein levels are upregulated in CRC, and this overexpression is associated with tumor size, tumor differentiation, lymph node metastasis, and distant metastasis." (PMID 32178475, 2020). "ELMO3 expression, T classification, N classification, histological classification, tumor localization and resection margins were included into calculation." (PMID 30374620, 2019). "The mean ELMO1, ELMO2, and ELMO3 methylation levels in the tumor biopsies were 6.8% (SD 3.9), 3.3% (SD 2.6), and 80.6% (SD 13.0), respectively." (PMID 29495584, 2018). "The promoter methylation levels of ELMO1 and ELMO2 were generally low, whereas ELMO3 methylation levels were high, in the tumor biopsies." (PMID 29495584, 2018). "The results revealed that ELMO3 expression in GC tumor tissues was significantly higher than in the paired adjacent tissues." (PMID 30345300, 2018). "CRC tumor tissues expressed markedly higher level of ELMO3 protein than paired adjacent normal tissues (p = 0.000)." (PMID 27999268, 2016). "To clarify the relationship between the expression of ELMO3 in CRC tissue and clinicopathological characteristics, we examined the mRNA and protein levels of ELMO3 in paired CRC tumor tissues and adjacent normal tissues." (PMID 27999268, 2016). "In conclusion, the results of our study show that the ELMO3 protein as a potential oncogene was overexpressed in CRC tumor tissues." (PMID 27999268, 2016). "The positive expression rate of the ELMO3 protein in the tumor tissues (88.9%) was higher than that in the adjacent normal tissues (37.78%) (p = 0.000)." (PMID 27999268, 2016). "However, tendencies were observed that patients with an ELMO1 hypermethylated tumor were unmethylated at the MGMT promoter (p = 0.053), and likewise that patients with an ELMO3 hypomethylated tumor were unmethylated at the MGMT promoter (p = 0.137)." (PMID 29495584, 2018). "In addition, ELMO3 was also highly expressed in tumor cell lines compared with its expression in normal gastric epithelial cells." (PMID 30345300, 2018). "It is possible that the regulatory mechanism of ELMO3 in cancers depends on the tumor type." (PMID 30345300, 2018). "Whether ELMO3 can form a complex with Dock180 to regulate Rac activation in tumor cell migration requires more evidence." (PMID 30345300, 2018). "This revealed that ELMO3 had a higher expression level in tumor cells than in normal cells." (PMID 30345300, 2018). "However, a tendency was observed for a shorter PFS in patients with an ELMO3 hypomethylated tumor (Hazard ratio; 1.48, 95% confidence interval; 0.89–2.47, p = 0.129)." (PMID 29495584, 2018). "Positive immunostaining of ELMO3 was significantly correlated with tumor size (p = 0.007), pathologic differentiation degree (p = 0.001), depth of invasion (p = 0.009), lymph node metastasis (p = 0.003), distant metastasis (p = 0.013) and TNM stage (p = 0.000)." (PMID 27999268, 2016). "ELMO3 was found to be highly methylated in all of the normal lung tissue samples, while significantly lower methylation levels were observed when analyzing the primary tumor samples (both patient cohorts combined versus normal lung tissue, p=0.022)." (PMID 25594031, 2014). "Therefore, the process of ELMO3 regulation of tumor growth and metastasis may be controlled by COX-2." (PMID 31134158, 2019). "Thus, this could support that our data reflect a worse therapeutic response for patients having a tumor with a hypomethylated ELMO3 promoter." (PMID 29495584, 2018). "Therefore, the mechanism whereby ELMO3 regulates GC cell invasion and metastasis could be very complicated and possibly differs in different tumor types." (PMID 30345300, 2018). "ELMO3 is a member of the engulfment and cell motility (ELMO) protein family, which plays a vital role in the process of chemotaxis and metastasis of tumor cells." (PMID 30345300, 2018).
tumor (continued). "Other tumor promoter genes described in NSCLC, such as ELMO3 and 14-3-3s, show similar patterns of promoter methylation/expression to those observed for TMPRSS4." (PMID 26989022, 2016). "Furthermore, we also discussed that whether ELMO3 might be modulated by Parecoxib, a COX2 inhibitor, for reducing tumor cell metastasis and recurrence of NSCLC." (PMID 31134158, 2019). "Therefore, Parecoxib may serve as a tool to study ELMO3 inhibition, and might be a potential candidate for the treatment of NSCLC, inhibiting tumor metastasis and preventing tumor recurrence." (PMID 31134158, 2019).
cancer (10 papers, 2014 to 2023). A tumor composed of atypical neoplastic, often pleomorphic cells that invade other tissues. "The hypothesis is that during cancer progression the promoter region of ELMO3 is demethylated which is associated with the formation of metastasis." (PMID 30374620, 2019). "Carcinoma ex pleomorphic adenoma: In patients with carcinoma ex pleomorphic adenoma 50% (two of four samples) showed high ELMO3 expression and 50% showed low ELMO3 expression." (PMID 30374620, 2019). "In line with the results of qPCR, the ELMO3 protein level in the GC cancer tissues was also significantly higher than in the paired adjacent tissues (P < 0.001)." (PMID 30345300, 2018). "The results showed that the mRNA level of ELMO3 was significantly higher in cancer tissues than in paired adjacent tissues from 48 paired specimens (P = 0.003)." (PMID 30345300, 2018). "In conclusion, the putative oncogene, ELMO3, becomes overexpressed in NSCLC in combination with DNA hypomethylation of its promoter, and this cancer-specific event is associated with the formation of metastases." (PMID 25594031, 2014). "In conclusion, the putative oncogene, ELMO3, is overexpressed in NSCLC in combination with hypomethylation of its promoter and these cancer-specific events are associated with the formation of metastases." (PMID 25594031, 2014). "DNA methylation changes in gene promoter CpG islands are responsible for altering the expression of many different tumor suppressor genes and oncogenes in cancer, including ELMO1 in gastric cancer and ELMO3 in lung adenocarcinoma, and associated brain metastases." (PMID 29495584, 2018). "The expression of ELMO3 could always be found in the cytoplasm of the cancer cells." (PMID 30374620, 2019). "However, remarkably little is known about the role of ELMO3 in cancer." (PMID 30345300, 2018). "This corresponds well with previous findings from other types of cancer, where promoter hyper- and hypomethylation have been observed in a subset of cases for ELMO1 and ELMO3, respectively." (PMID 29495584, 2018). "ELMO1 and ELMO2 are highly expressed in most human cancer tissues, whereas ELMO3 is only found in some cancer tissues, and its function has not been fully clarified in GC." (PMID 30345300, 2018). "The engulfment and cell motility 3 (ELMO3) gene plays an important role for the migratory potential of cells, but have not previously been studied in primary samples from cancer patients." (PMID 25594031, 2014). "The expression of ELMO3 in malignant tumors of minor salivary glands has not been studied so far." (PMID 30374620, 2019). "However, the role and function of ELMO3 are rarely characterized due to its low or absent expression in most cancer tissues or cell lines." (PMID 27999268, 2016). "Furthermore, ELMO3 expression has not previously been analyzed in primary samples from cancer patients." (PMID 25594031, 2014). "In addition, studies have reported that the expression of ELMO3 in patients with distant metastases was significantly higher than that in patients without distant metastases in NSCLC patients, and therefore ELMO3 may be a direct driver of cancer metastasis." (PMID 31134158, 2019).
adenocarcinoma (1 paper, 2019). A common cancer characterized by the presence of malignant glandular cells. "Adenocarcinoma: In adenocarcinoma 50% (three of six samples) of the samples showed high ELMO3 expression and 50% low ELMO3 expression." (PMID 30374620, 2019).
ELMO3 also shares sentences with these, for which no sentence is quoted: laryngeal carcinoma (3 papers); salivary gland adenoid cystic carcinoma (3); Sensory hearing loss (2); head and neck cancer (1); hepatic cancer (1); kidney cancer (1); metastasis (1); salivary gland carcinoma (1); squamous-cell carcinoma of (1).